TNF (tumor necrosis factor)
Diseases named in the same sentence as TNF in open-access papers (continued):
Sharing a sentence is not in itself a finding about the gene and the disease.
psoriasis (continued). "Mechanistically, vitamin D inhibits Th17-driven inflammation and suppresses pro-inflammatory cytokines like IL-12/23 and TNF-α, which are overexpressed in psoriasis, thus improving skin barrier function by regulating proteins such as psoriasin and late cornified envelope proteins." (PMID 39796035, 2024). "Moreover, contrary to expectations, the de novo emergence of psoriasis and less commonly IBD has been associated with anti-TNF-α medication." (PMID 39463646, 2024). "In severe or refractory psoriasis, guidelines recommend using biological therapies directed against TNF-alpha (adalimumab, etanercept, certolizumab, infliximab) or the IL-23/17 axis (ustekinumab, guselkumab, risankizumab, tildrakizumab, brodalumab, ixekizumab, secukinumab, bimekizumab)." (PMID 38610706, 2024). "On the contrary, a lower number of innate immunity cells (BDCA2+ plasmacytoid dendritic cells, CD15+ neutrophils, CD117+ mast cells) and reduced IFN-α/β, lymphotoxin (LT)-α/β, were observed in anti-PD-1-induced psoriasis lesions, as compared with anti-TNF-α-induced paradoxical psoriasis." (PMID 38495872, 2024). "Psoriasis is an inflammatory skin disease characterized by the hyperproliferative epidermal keratinocytes and significant immune cells infiltration, leading to cytokines production such as IL-1β, TNF-α, IL-23, and IL-17." (PMID 38704587, 2024). "Adalimumab, a human anti-TNF monoclonal antibody (mAb), is approved for CD, psoriasis, RA, and UC." (PMID 39297883, 2024). "In psoriasis, decreased levels of adiponectin in the blood have been observed, especially in patients with severe disease, and these levels are negatively correlated with blood levels of IL-6 and TNF-α." (PMID 38929716, 2024). "Moreover, circulating CD4+ T cells in psoriasis are enriched in TNF-α+ cells compared to healthy controls." (PMID 38642273, 2024). "The availability of anti-TNF-a drugs in psoriasis has given some hope in CTCL treatment." (PMID 38607023, 2024). "The expression of beta-defensins in psoriasis lesional skin is induced by TNF-α and IFN-gamma." (PMID 38666958, 2024). "The psoriasis treatment guideline of the American Academy of Dermatology mentions that IBs (anti-TNF, anti-IL12/23, anti-IL17 and anti-IL23) can be used in patients with HIV infection, provided they are receiving ART, have normal CD4, undetectable viral load and do not have recent OIs." (PMID 38238209, 2024). "However, neither RSL3 nor erastin elicited histological epidermal changes or immune cell infiltration in the skin characteristic of psoriasis, while skin TNF-α and IL-1β expressions were elevated by RSL3 treatment." (PMID 39570671, 2024). "The exact pathogenesis of psoriasis remains unclear; however, the activation of T cells and heightened pro-inflammatory cytokine activity, particularly that of tumor necrosis factor (TNF)-∂, have received increased attention." (PMID 38705919, 2024). "Since NFκB also plays a significant role in the development of skin diseases such as cancer and psoriasis, while its expression is strongly induced by TNFα, reducing its expression by combining CBG+CBD might be beneficial to prevent those skin diseases." (PMID 38891097, 2024). "Furthermore, macrophages are an important source of TNF-α in skin injury, which is known to be a very essential cytokine in the pathologic process of psoriasis." (PMID 38832986, 2024). "Several biological effects of TNF are mediated by NF-κB activation, including cellular proliferation, differentiation, and apoptosis, so that NF-κB is considered an essential nuclear transcription factor in the pathogenesis of psoriasis." (PMID 39057409, 2024). "The presence of IFN-γ and TNF-α may augment the potential effects of IL-17A on the pathogenesis of psoriasis and atherosclerosis." (PMID 39104857, 2024). "Notably, IL-6 and TNF-α levels are elevated in both psoriasis and SDs and have been proven to induce keratinocyte hyper-proliferation in psoriasis;." (PMID 39411067, 2024).
psoriasis (continued). "Through this analysis of the immune pathways involved in psoriasis, therapeutic strategies have shown promising results in recent years, in particular with regard to biologics such as anti-IL-17, anti-IL-23, and anti-TNF-α." (PMID 39767248, 2024). "Activated plasmacytoid dendritic cells by genetic and/or environmental factors produce large amounts of pro‐inflammatory cytokines [(such as interleukin (IL)‐17, IL‐22, IL‐23, IL‐1β, interferon (IFN)‐γ, and tumor necrosis factor (TNF)‐α], which can then trigger the onset of psoriasis." (PMID 39167035, 2024). "Only 15.6% of the patients in the psoriasis group received systemic treatment targeting TNF-α." (PMID 39044928, 2024). "Elevated TNF-α, IL-1β, and IL-6 levels in psoriasis reduce triglyceride clearance." (PMID 38683749, 2024). "Interestingly, pro-inflammatory cytokines that are upregulated in psoriasis (such as TNF-α, Toll-IL-1R (TIR), and IL-1β) also upregulate miR-9." (PMID 39796035, 2024). "From this, we inferred that specifically receiving too much TNF signaling and sending too much IL16 signaling may make IS CD8+ T cells a pathogenic subpopulation in psoriasis." (PMID 38915827, 2024). "Moreover, a statistically significant diminution in TNF-α levels was specifically observed in psoriasis and CFS patients, underscoring the therapeutic potential of targeting gut microbiota in managing inflammatory conditions." (PMID 38585146, 2024). "Importantly, in a systematic review of 17 studies of TNFα-induced paradoxical psoriasis, switching to UST resulted in complete or partial resolution of psoriasis in 83.1% of patients (n = 89)." (PMID 39200303, 2024). "Furthermore, TNF-α antagonists have been found to reduce bone damage in patients with erosive arthritis and psoriasis." (PMID 38473934, 2024). "The safety profile of anti-TNF-α drugs has been discussed in a previous section (see Psoriasis)." (PMID 38521706, 2024). "IL-17A alone is insufficient for a substantial inflammatory response and may cooperate with other cytokines (such as TNF-α, IL-23, IL-1β, IL-6, and IL-22) to amplify the proinflammatory cascade characteristic of psoriasis." (PMID 38446584, 2024). "This study aimed to investigate the effects of IFN-γ and a cytokine mix (5MIX: IL-1α, IL-17A, IL-22, OsM, and TNF-α) on the antigen-presenting capabilities of keratinocytes, with a specific focus on immune-mediated dermatological conditions such as psoriasis (Ps)." (PMID 39769151, 2024). "Recent literature expounded that people with a background of rheumatological or gastrointestinal disorders may experience induced new-onset psoriasis while receiving TNF inhibitors." (PMID 38335182, 2024). "Therefore, we plan to verify in a future study the role of POE in an in vitro model of psoriasis using both the hyperproliferative model of LPS/IL-22-stimulated HaCaT cells and the inflammatory model of HaCaT cells stimulated with LPS/TNF-α." (PMID 39057409, 2024). "However, the mechanisms whereby, the neutrophils contribute to the occurrence of psoriasis is attributed to their ability to secrete various cytokines and chemokines such as TNF-α, IL-17, and IL-36 family factors, as well as neutrophil extracellular traps." (PMID 39795946, 2024). "The oxidative stress model of HaCaT psoriasis was established by TNF-α and IL-17A in vitro." (PMID 38799436, 2024). "In this study, while the incidence of paradoxical eczema in biologic-treated patients with psoriasis was low overall, it was highest in those receiving IL-17 inhibitors followed by those receiving TNF inhibitors, those receiving IL-12/23 inhibitors, and those receiving IL-23 inhibitors." (PMID 38055239, 2024). "In the PPI network analysis, TNF, a known target of psoriasis, is strongly correlated with AIF1." (PMID 39883516, 2024).
psoriasis (continued). "Furthermore, we examined a set of inflammatory cytokines, including IL-17A, IL-23A, IL-1β, TNF-α, IL-6, and IL-22, at the mRNA level in LPS-induced psoriatic keratinocytes, which are closely related to psoriasis in vivo." (PMID 39109246, 2024). "Moreover, drugs currently approved for psoriasis treatment, such as TNF-α antagonists, IL-12/IL-17 inhibitors, and glucocorticoids, exert inhibitory effects on the NF-κB signaling pathway." (PMID 39465158, 2024). "By downregulating S100A7 expression, this may decrease the production of TNF, IL-6, and IL-8 from neutrophils, which are known to play a crucial role in the pathogenesis of psoriasis." (PMID 38699235, 2024). "In some cases, medication with TNF-α inhibitors has successfully treated ICI-induced psoriasis." (PMID 39795946, 2024). "Infliximab is a humanized anti-TNF mAb that is indicated for CD, psoriasis, RA, and UC." (PMID 39297883, 2024). "Skin is a tissue in which failure of the regulation of the TNFR1 signalling pathway by TNF-α could induce inflammatory diseases such as psoriasis and atopic dermatitis." (PMID 38789573, 2024). "A recent study observed that TNF-α inhibitors led to significant improvements in clinical symptoms and a rapid and substantial decrease in the number of osteoclast precursors in the peripheral blood of psoriasis patients with erosive arthritis." (PMID 38473934, 2024). "Dual blockage of TNF-α and IL-17A repressed the inflammatory psoriasis phenotype." (PMID 39558145, 2024). "In psoriasis patients, IL-17A may synergize with other inflammatory cytokines like TNF-α and IFN-γ, enhancing its effects on atherosclerosis." (PMID 39104857, 2024). "In the present study, we found that BAC could relieve symptoms of psoriasis through the suppression of proliferation and production of cytokines in TNF-α/LPS-induced HaCaT cells." (PMID 37298949, 2023). "TNF-α is recognized for its ability to hinder the generation of adiponectin, which explains the lower levels of adiponectin observed in individuals with psoriasis compared to healthy individuals." (PMID 37895330, 2023). "Studies have found that TNF-α blockers used in the treatment of psoriasis patients may help alleviate their depressive symptoms, further indicating the potential connection between psoriasis and depression." (PMID 37868345, 2023). "Psoriasis is a quintessential immune-mediated inflammatory disorder, marked by heightened levels of proinflammatory markers and cytokines, including, but not limited to, tumor necrosis factor (TNF)-α, IL-6, IL-17, IL-22, and IL-238,9." (PMID 38102220, 2023). "Furthermore, chemerin was found to activate NF-κB and stimulate the expression of the pro-inflammatory cytokines IL-8, IL-6, and TNF-α, which are crucial in psoriasis pathogenesis." (PMID 37047363, 2023). "The small molecule drug apremilast (marketed under the trade name Otezla® by Amgen Inc., Thousand Oaks, CA), a selective inhibitor of the enzyme phosphodiesterase 4 (PDE4) that inhibits production of TNF-α by rheumatoid synovial cells, among others, is increasingly being used to treat psoriasis." (PMID 37469991, 2023). "Here we established and quantified an association of the use of TNF inhibitors, as well as the non-TNF inhibitors studied with the exception of tofacitinib, with the risk of psoriasis AEs." (PMID 37369753, 2023). "At present, three main biologics, i.e., etanercept, infliximab, and adalimumab, are used to treat psoriasis by targeting TNFα to prevent TNF-mediated cellular responses and modulate biological responses that are controlled by additional downstream molecules induced or regulated by TNFs." (PMID 38008779, 2023). "The neutrophil-to-lymphocyte ratio (NLR), the platelet-to-lymphocyte ratio (PLR), and the systemic immune–inflammation index (SII) were measured in patients with psoriasis initiating TNF-α inhibitors (n = 131), IL-17/IL-17R inhibitors (n = 65), or IL-23/IL-12/23 inhibitors (n = 50)." (PMID 37047086, 2023).
psoriasis (continued). "Although the etiology is not fully understood, psoriasis is characterized by keratinocyte hyperproliferationa and an increased secretion of inflammatory cytokines including interleukin (IL)-17, IL-21, IL-23, and tumor necrosis factor (TNF)-alpha." (PMID 36769020, 2023). "Immunologically speaking, psoriasis may coexist with IBD, establish a bidirectional causative relationship, or can be a paradoxical adverse event of anti-TNF therapy." (PMID 38003284, 2023). "The TNF blockade has been validated as a therapeutic strategy for psoriasis." (PMID 37685578, 2023). "Thus, we explored the impact of cytokine-blocking agents (IL-17 or TNF inhibitors) on DNA methylation patterns in “all” psoriasis patients." (PMID 37662940, 2023). "A downregulation in CASP5 mRNA expression was observed in the lesional skin of psoriasis patients treated with a TNF inhibitor compared to their skin lesions before the start of the respective therapy, indicating a prevention of TNF-induced inflammasome priming." (PMID 37325658, 2023). "While head-to-head trials have shown dual blockade of IL-17A and IL-17F to be superior to biologic targeting IL-17A, IL-12/23, TNF-α in patients with psoriasis, further data is required to confirm whether this finding replicated in patients with PsA." (PMID 37731935, 2023). "However, increasing numbers of cases of paradoxical development of psoriasis in patients with autoimmune diseases treated with TNF-α inhibitors have been reported in the literature." (PMID 37664349, 2023). "Furthermore, keratinocytes play a role in the development of psoriasis as immune cells by secreting antibacterial peptides, chemokines, tumor necrosis factor-α, interleukin (IL)-36, and IL-23." (PMID 38022549, 2023). "In psoriasis patients, a higher ratio of M1 to M2 macrophages could be reduced using TNF-α inhibitors, such as adalimumab." (PMID 38239345, 2023). "TNF-α inhibition has indeed been shown to be highly effective for the treatment of psoriasis." (PMID 37443800, 2023). "Interleukin-23 (IL-23) and tumor necrosis factor α (TNF-α) play pivotal roles in psoriasis, and their corresponding inhibitors are recommended for first-line treatment of moderate to severe plaque psoriasis by the American Academy of Dermatology-National Psoriasis Foundation guidelines." (PMID 37275851, 2023). "Furthermore, they postulated that PCSK9 is connected with a higher atherosclerotic burden in psoriasis patients, and, using blood transcript analysis, they identified TNF, IL6, IL17A, and IL23 as PCSK9-related pathways." (PMID 37234169, 2023). "In psoriasis, a study evaluated the influence of the SLCO1C1 rs3794271 and PDE3A rs11045392 polymorphisms on anti-TNF response in 130 white patients (from Spain) and showed that patients carrying the C allele obtained a better response (ΔPASI after 3 months) (p = 0.00057)." (PMID 37240048, 2023). "Tumor necrosis factor-alpha (TNF-α), interleukin-1 alpha (IL-1α), interleukin-17A (IL-17A), interleukin-22 (IL-22), and oncostatin M (OSM) are closely associated with the pathogenesis of psoriasis." (PMID 36999136, 2023). "It had been reported that TNF plays a vital role in psoriasis development." (PMID 37531036, 2023). "In vitro, Onercept neutralized TNF but failed in psoriasis clinical trials." (PMID 36831151, 2023). "An anti-TNF-α antibody may reduce CV events in psoriasis patients, whereas the ability of an anti-IL-12 antibody to reduce CV events remains to be clarified." (PMID 37833247, 2023). "We also examined the effect of DOPG on inflammation in the imiquimod-induced mouse model of psoriasis and found that topical application of DOPG decreased the imiquimod-stimulated inflammation and TNFα immunoreactivity and improved skin lesions in this in vivo psoriasis model." (PMID 37242739, 2023). "Increased levels of IL-6 and TNF-α were observed in serum after psoriasis." (PMID 36982669, 2023).
psoriasis (continued). "The C-reactive protein and PLR might act as biomarkers reflecting a treatment response to TNF-α inhibitors in patients with psoriasis." (PMID 36769622, 2023). "Currently, four classes of biologics are available for psoriasis treatment: inhibitors of TNF-α (adalimumab, etanercept, infliximab and certolizumab pegol), IL-17 (secukinumab, brodalumab and ixekizumab), IL-23 (tildrakizumab, risankizumab and guselkumab) and IL-12/23 (ustekinumab)." (PMID 37631238, 2023). "NLR and IL-6 may serve as predictive biomarkers of treatment response to TNF-α inhibitor therapy in patients with psoriasis." (PMID 37047086, 2023). "Antagonization of TNFα with etanercept attenuated psoriasis severity in a clinical trial." (PMID 36901755, 2023). "Moreover, concerns regarding the enhanced risk of cancer have been raised with other immunosuppressive treatments for psoriasis, such as anti–TNF inhibitors, due to the role of TNF in cancer growth inhibition." (PMID 37615258, 2023). "Also, treatment of psoriasis patients with etanercept, an anti-TNF-α antibody, reversed filaggrin and loricrin downregulation." (PMID 37834081, 2023). "Next, the putative anti-inflammatory effects of DMG-Na were assessed on cultured human HaCaT keratinocytes stimulated with the combination of 25 ng/mL of interferon-γ (INFγ) + 25 ng/mL of TNFα, a well-established in vitro model of inflammatory skin diseases including, but not limited to, psoriasis." (PMID 37511024, 2023). "Furthermore, TNF-α, a key cytokine in the pathogenesis of psoriasis, reportedly decreased filaggrin and loricrin expression in human keratinocytes." (PMID 37834081, 2023). "Stored cholesterol further leads to disordered lipid metabolism under the action of inflammatory factors in the inflammatory environment of psoriasis, such as interferon gamma and tumor necrosis factor alpha, in the mouse model by changing the pH of lysosomes and free cholesterol load." (PMID 38149053, 2023). "Although precise anti-inflammatory signalling pathways of noscapine in psoriasis induction are still unknown, we hypothesise that noscapine's antiproliferative and anti-inflammatory activity occurs via TNF-α /IFN-γ reduction." (PMID 37663384, 2023). "The first TNF inhibitor authorized for the treatment of psoriasis was etanercept." (PMID 37965393, 2023). "Targeting cytokines such as TNFα, IL‐1 or IL‐6 might reduce mood and CI in systemic inflammation, as has been demonstrated in other conditions like psoriasis." (PMID 38146805, 2023). "In particular, the introduction of biologic drugs specifically targeting interleukins (IL) 23 and 17 and tumor necrosis factor-alpha (TNFα), involved in psoriasis pathogenesis, revolutionized the management of the disease, showing promising results in terms of effectiveness and safety." (PMID 37626687, 2023). "A 2004 study using mouse models highlighted the role of TNF-α in the pathogenesis of psoriasis." (PMID 37664349, 2023). "Our models highlight that modulating the Wnt pathway, involved in psoriasis development through its role in hyperproliferation of keratinocytes and angiogenesis, could be related to anti-TNF efficacy." (PMID 37809085, 2023). "TNF- (tumor necrosis factor) plays an important role in the pathophysiology of psoriasis." (PMID 36995575, 2023). "The reported frequencies of psoriasis AEs were calculated for each TNF inhibitor monotherapy." (PMID 37369753, 2023). "In addition to the crucial role played by autoreactive T cells and cytokine populations, the IL-23/Th17 pathway and the TNFα-IL-23-Th17 axis is a central signaling pathway that plays a pivotal role in T cell-mediated psoriasis." (PMID 38239345, 2023). "Etanercept could prevent TNF-induced endothelial cell apoptosis, while Adalimumab could improve endothelial function and inflammation in patients with psoriasis." (PMID 37629526, 2023). "However, the effectiveness of TNF-α inhibitors in psoriasis is based on indirect adaptive immune modulations, especially on the IL-23/IL-17A axis." (PMID 38239345, 2023).